FAM3B (FAM3 metabolism regulating signaling molecule B)
Diseases named in the same sentence as FAM3B in open-access papers (continued):
Sharing a sentence is not in itself a finding about the gene and the disease.
tumor (10 papers, 2005 to 2025). "In order to identify mechanisms underlying the tumor growth promotion by FAM3B in nude mice, we performed gene expression analysis by RT-PCR and immunohistochemistry in dissected tumor samples." (PMID 29357840, 2018). "Notably, deletion-derived fusions correlated with aggressive tumor behavior, potentially due to concurrent loss of interstitial genes (e.g., FAM3B) that modulate prognosis." (PMID 40746562, 2025). "The qRT‐PCR analysis showed that FAM3B mRNA expression was up‐regulated in 85% (34/40) of the tumour samples compared with matched adjacent normal tissues (P < 0.01)." (PMID 30565387, 2019). "Tumours removed from the left armpit were markedly larger in volume than those taken from the right side (P < 0.01), which suggested that FAM3B increased tumour growth in vivo mouse model." (PMID 30565387, 2019). "Our expression data indicated that FAM3B expression is elevated in ESCC tumour cells and cell lines, and showed a positive correlation between FAM3B expression level and T/TNM stage." (PMID 30565387, 2019). "In summary, our study is the first to demonstrate that FAM3B functions as a tumour promoter in the progression of oesophageal carcinoma." (PMID 30565387, 2019). "The immunohistochemistry analysis of tumor xenografts revealed a similar anti-apoptotic phenotype displayed by FAM3B-overexpressing tumor cells." (PMID 29357840, 2018). "When compared to the respective controls, cells overexpressing FAM3B displayed a decreased anchorage- independent growth in vitro and increased tumor growth in xenografted nude mice." (PMID 29357840, 2018). "FAM3B plays an important role in tumor development, disease prognosis, and drug resistance." (PMID 37251343, 2023). "The results showed that high expression of FAM3B in TNBC tumor tissues was related to poor prognosis in patients, suggesting that FAM3B may play a carcinogenic role in TNBC." (PMID 37251343, 2023). "In addition to identifying its role in glycolipid metabolism, research on FAM3B focuses on its biological role in tumour progression." (PMID 30565387, 2019). "In addition, immunohistochemical data indicates that, at least in part, FAM3B promotes tumorigenicity in these cells by the upregulation of Bcl-2 and downregulation of Bax, with a high correlation between tumor growth and FAM3B/Bcl-2 gene expression." (PMID 29357840, 2018). "Thus, we conclude that FAM3B-mediated upregulation of Bcl-2 anti-apoptotic family members can contribute to apoptosis inhibition and, consequently, increased of tumor growth in mice xenotransplanted with DU145 cells." (PMID 29357840, 2018). "Moreover, we observed a statistically significant correlation when comparing the tumor mass from animals with FAM3B gene expression (r = 0.8932; p = 0.0062) and Bcl-2 gene expression (r = 0.9274; p = 0.0026) in all animals." (PMID 29357840, 2018). "Interestingly, the roles of FAM3B in the regulation of tumor cell behaviors have been preliminarily described." (PMID 28536423, 2017). "The presence of several blood vessels and hemorrhagic features in tumors as well as micrometastases detected exclusively in lungs from animals injected with DU145/FAM3B cells suggests that FAM3B may also promote angiogenesis, which plays a major role in a metastatic tumor phenotype." (PMID 29357840, 2018). "Thus, the regulation of cell proliferation and migration by FAM3B could be universally occurring in VSMCs and tumor cells." (PMID 28536423, 2017). "That is, FAM3B protein was located primarily in the nucleus of ESCC cells and was expressed at a higher level in tumour tissue than in adjacent normal tissue." (PMID 30565387, 2019). "Our functional experiments confirmed that overexpression of FAM3B inhibits ESCC cell death, increases tumour growth in vivo and promotes ESCC cell migration and invasion." (PMID 30565387, 2019).
tumor (continued). "A prognostic signature based on RGs (AGTR1, CTGF, FAM3B, IL11, IL17C, PTH2R and SPAG11A) performed moderately in prognostic predictions and correlated with age, tumor stage, metastasis, number of lesions, and tumor burden." (PMID 30661062, 2019). "NF2, FAM3B, and MGMT are primarily involved in regulating the tumor immune microenvironment." (PMID 37264476, 2023). "In summary, our results show that overexpression of FAM3B leads to increased expression of Bcl-2 and Bcl-XL, which results in the inactivation of caspases and decreases the rate of DU145 cells undergoing apoptosis, consequently promoting an increased tumor growth." (PMID 29357840, 2018).
FAM3B also shares sentences with these, for which no sentence is quoted: colorectal cancer (2 papers); melanoma (2); viral infection (2); colon adenocarcinoma (1); gestational diabetes (1); gonococcal infections (1); metabolic syndrome (1); Müllerian agenesis (1); neuroblastoma (1); nonalcoholic fatty liver disease (1); Obesity (1); oral squamous cell carcinoma (1); pneumonia (1); rash (1); Sepsis (1); steatosis (1).